LRP1B (LDL receptor related protein 1B)
Description:
Potential cell surface proteins that bind and internalize ligands in the process of receptor-mediated endocytosis.
Synonyms: LRP-1B; LRP-DIT; LRPDIT
Tractability: Antibody: UniProt predicts a signal peptide or a membrane-spanning region; its Gene Ontology location is reachable by antibodies, with medium confidence. PROTAC: its protein half-life has been measured.
Gene: Protein-coding gene on chromosome 2 (140,231,423 to 142,131,016, reverse strand). Ensembl gene ENSG00000168702.
Subcellular location: Membrane
Subcellular location (Human Protein Atlas): Vesicles
Gene Ontology:
Molecular function: protein binding; low-density lipoprotein particle receptor activity; calcium ion binding
Biological process: protein transport; receptor-mediated endocytosis
Cellular component: receptor complex; plasma membrane; membrane
Genetic constraint (gnomAD): Loss-of-function variants: 155 observed, 422.69 expected, observed/expected ratio (o/e) 0.37, 90% interval 0.32 to 0.42. The upper end of that interval is the gene's LOEUF score, 0.42, which puts it in group 1 of 6, group 1 being the genes least tolerant of losing a copy. Missense variants: 4,027 observed, 4,652.6 expected, observed/expected ratio (o/e) 0.87, 90% interval 0.84 to 0.89. Synonymous variants: 1,667 observed, 1,581.6 expected, observed/expected ratio (o/e) 1.05, 90% interval 1.01 to 1.1.
Cancer hallmarks: invasion and metastasis (suppresses); suppression of growth (promotes)
Homologues: Orthologues: chimpanzee LRP1B (99% identical), macaque LRP1B (99% identical), dog LRP1B (97% identical), rabbit LRP1B (96% identical), pig LRP1B (96% identical), mouse Lrp1b (92% identical), guinea pig LRP1B (87% identical), rat Lrp1b (85% identical), tropical clawed frog LRP1B (80% identical), zebrafish lrp1bb (69% identical), zebrafish lrp1ba (52% identical), Drosophila melanogaster arr (8% identical). Paralogues in human: LRP1 (60% identical), LRP2 (34% identical), LRP4 (11% identical), LRP6 (10% identical), LRP5 (10% identical), LRP8 (7% identical), VLDLR (7% identical), EGF (6% identical), NID1 (5% identical), NID2 (5% identical), LRP3 (4% identical), and 2 more.
Diseases named in the same sentence as LRP1B in open-access papers:
LRP1B is named in the same sentence as 136 diseases in open-access papers, as found by Europe PMC text mining. Sharing a sentence is not in itself a finding about the gene and the disease. The quoted sentences say what the papers report.
melanoma (36 papers, 2013 to 2025). A malignant, usually aggressive tumor composed of atypical, neoplastic melanocytes. "We also identified LRP1B, which is a target of recurrent somatic mutations in melanoma, exemplifying a potential interplay between germline and somatic events in melanomagenesis." (PMID 38308491, 2024). "Patients with LRP1B mutation were identified to be associated with prolonged survival in both melanoma and NCLC cohorts." (PMID 35389768, 2022). "The mutation of LRP1B was correlated with ameliorative immunotherapy outcomes for melanoma and non‐small cell lung cancer (NSCLC) patients." (PMID 35150083, 2022). "In particular, LRP1B mutation was identified as a biomarker for ICIs in melanoma, non-small cell lung cancer 17, prostate cancer 18, and advanced biliary tract cancer." (PMID 33994859, 2021). "Recently, LRP1B mutation status was associated with improved patients’ outcome to immunotherapy, being described as a biomarker for ICIs in multiple cancers such as melanoma, non-small cell lung cancer, prostate cancer, and advanced biliary tract cancer." (PMID 34577535, 2021). "Chen and his colleagues have revealed that higher TMB was found in LRP1B mutated patients with melanoma and non-small cell lung cancer." (PMID 33391418, 2021). "For example, melanoma patients with LRP1B mutations exhibited a higher mutational load than those with the wild-type gene." (PMID 32843031, 2020). "Frequently inactivation mutation of LRP1B was observed in melanoma, lung cancer, esophagus squamous-cell carcinoma, head and neck squamous cancer, gastric cacner, and so on." (PMID 31164891, 2019). "In Kaplan-Meier survival analysis, the LRP1B mutation was significantly associated with a better immunotherapy survival outcome in the pooled melanoma cohort (log-rank test, P = 0.005)." (PMID 31164891, 2019). "This is also the case in predicated neoantigen peptides which caused by LRP1B mutation (median, melanoma: 181 vs. 199, p = 0.293; NSCLC: 124 vs. 167, p = 0.079)." (PMID 31164891, 2019). "Melanoma samples with LRP1B mutations had a significantly higher tumor mutation burden and neoantigen burden by Wilcoxon rank sum test (log2 TMB, 9.5 vs. 7.3, P < 0.001; log2 NB, 9.2 vs. 6.9, P < 0.001)." (PMID 31164891, 2019). "LRP1B was one of the most frequently mutated genes in the aggregated melanoma cohort, accounting for 122 of 332 patients (36.7%)." (PMID 31164891, 2019). "We analyzed LRP1B mutation with immune response and outcome in 332 samples from the melanoma immunotherapy cohort and 113 samples from the NSCLC immunotherapy cohort for further corroboration." (PMID 31164891, 2019). "LRP1B was frequently mutated in melanoma and NSCLC, and its mutation was associated with higher TMB and better survival outcome." (PMID 31164891, 2019). "Missense mutations in Lrp1b, a negative regulator of Wnt signaling, have been found earlier in Braf mutant human melanoma." (PMID 23845441, 2013). "LRP1B mutation could potentially be used as a biomarker to anticipate the immune response and is linked to extended survival in melanoma and NSCLC immunotherapy groups." (PMID 40492126, 2025). "Alterations in LRP1B were associated with high TMB in melanoma and non-small-cell lung cancer." (PMID 36333792, 2022). "Similarly, in a recent report, analyzing mutations in a single gene of LRP1B can be used to predict TMB in melanoma patients." (PMID 34093808, 2021). "Similarly, LRP1B gene not only has a relatively high mutation frequency (34.78%, 176/506) in this study, but also frequently mutates in multiple tumors, such as melanoma, ESCA and colorectal cancer (CRC)." (PMID 35069585, 2021). "Higher TMB was found in LRP1B mutated patients with melanoma and non-small cell lung cancer." (PMID 34720757, 2021).
melanoma (continued). "A previous melanoma study reported that LRP1B mutation was enriched in responders (34%) to immune checkpoint inhibitors (ICIs) compared with non-responders (3%) 13, which suggested LRP1B mutation may be an independent predictor for the response to ICI." (PMID 33994859, 2021). "LRP1B, a member of the low-density lipoprotein receptor family and an important tumor suppressor gene, had been reported giving raise to increasing mutation burden in melanoma, pointing to high-TMB." (PMID 33014052, 2020). "LRP1B (low-density lipoprotein receptor-related protein 1B) is frequently mutated in melanoma, non-small cell lung cancer (NSCLC) and other tumors; however, its association with TMB and survival in patients with immunotherapy remains unknown." (PMID 31164891, 2019). "Besides melanoma and non-small cell lung cancer, LRP1B was also frequently mutated in multiple types of human cancer." (PMID 31164891, 2019). "As the high prevalence of LRP1b mutation has been shown in PCa and a correlation between LRP1b mutation and the ICI response has been shown in melanoma patients, the authors hypothesized that LRP1b mutations may represent a surrogate marker for the mutational load." (PMID 37511177, 2023). "In recent years, a few studies have found that LRP1B has a high mutation frequency in malignancies such as lung cancer, HCC, and melanoma." (PMID 36282125, 2023). "A similar outcome was observed in the melanoma cohort, wherein the LRP1B mutant population showed better overall survival (OS) after immunotherapy." (PMID 36204371, 2022). "Several studies have suggested that LRP1B mutation was correlated with high TMB and improved outcomes with ICIs monotherapy in melanoma, NSCLC, and other solid tumors, which are consistent with our results in ICIs plus chemotherapy." (PMID 35902848, 2022). "LRP1B mutation is associated with a higher TMB and better survival outcomes in patients with melanoma and NSCLC." (PMID 35911687, 2022). "In melanoma and NSCL patients, LRP1B-mutated patients were shown to present enriched antigen presentation and interferon-related circuits as well as higher T cell-inflamed gene expression." (PMID 34577535, 2021). "TMB of melanoma patients in the LRP1B mutant group was significantly higher than that in the wild group." (PMID 34093808, 2021). "LRP1B mutation can be used as a biomarker to predict the TMB and efficacy of immunotherapy for melanoma and non-small cell lung cancer." (PMID 34093808, 2021). "Meanwhile, mutation in LRP1B were identified to be associated with better immunotherapy survival outcome in non-small cell lung cancer (NSCLC) and melanoma patients." (PMID 33976731, 2021). "The top 10 mutated genes in melanoma were TTN (72%), MUC16 (67%), DNAH5 (49%), PCLO (44%), LRP1B (38%), ANK3 (32%), DNAH7 (32%), ADGRV1 (35%), RP1 (33%), and BRAF (51%)." (PMID 33758620, 2021). "Mutations in LRP1B, the low‐density lipoprotein (LDL) receptor family gene, have been associated with high TMB and improved immunotherapy outcome in melanoma and NSCLC cancer." (PMID 32898339, 2020). "The top 10 mutated genes in 467 melanoma patients are TTN (72%), MUC16 (67%), BRAF (51%), DNAH5 (49%), PCLO (44%), LRP1B (38%), ADGRV1 (35%), RP1 (33%), ANK3 (32%), DNAH7 (32%)." (PMID 33072607, 2020). "Mutations of LRP1B are associated with increased TMB and survival in melanoma and non-small cell lung carcinoma patients given immunotherapy." (PMID 32110280, 2020). "Indeed, previous studies have associated LRP1B deletions and mutations with high TMB in several types of cancer, including melanoma, lung, and hepatic cancer, reflecting a high genomic instability." (PMID 37511044, 2023). "Besides LRP1B mutations associating with prognosis/survival in cancer patients, including GB, LRP1B mutations have been associated with higher tumor mutation burden (TMB) and better prognosis in lung cancer and melanoma patients." (PMID 37511044, 2023).
melanoma (continued). "Additionally, in melanoma and NSCL patients, LRP1B mutations significantly associated with a better ICI survival outcome, even after excluding the potential effect of other factors, such as TMB." (PMID 34577535, 2021). "Additionally, LRP1B have been described as a bona fide driver gene in many tumors, including liver, melanoma, colon, lung, gastric, ovarian, and breast." (PMID 34680332, 2021). "A retrospective multicenter study with 101 patients, including, but not limited to, melanoma patients, has suggested better outcomes to immune checkpoint blockade for patients with alterations in the tumor suppressor gene LRP1b (low-density lipoprotein receptor-related protein 1b)." (PMID 33435389, 2021). "However, LRP1B (regulated in trans by rs10811592 within the rs871024 locus; 9p21.3, in not sun‐exposed skin) was previously linked to melanoma through observations of recurrent somatic mutations within the gene." (PMID 38308491, 2024). "Additionally, previous studies reported that other genes are frequently mutated in melanoma and other cancer types, including BRCA2 (9/112, 8%), LRP1B (9/112, 8%), MET (8/112, 7%), PRKDC (7/112, 6%), NOTCH4 (7/112, 6%), CCND3 (6/112, 5%), and FGF3/4/19 (6/112, 5%)." (PMID 37649078, 2023). "Moreover, methylation of 6 CpGs of LRP1B were significantly associated with melanoma-specific survival (FDR < 0.05); the most significant of those CpGs was cg02322989, the hypomethylation of which was associated with higher melanoma-specific survival." (PMID 35840550, 2022). "Moreover, in melanoma and NSCL patients, cell cycle regulation and antigen processing and presentation pathways were significantly altered in samples from patients bearing LRP1B mutations." (PMID 34577535, 2021). "Melanoma samples with LRP1B mutations had higher mutation rate than samples without LRP1B mutation." (PMID 31164891, 2019). "In TCGA database, patients with LRP1B mutation have no benefits on conventional chemotherapy in melanoma and NSCLC, but displayed preferable clinical outcome in immune check-point blockades therapy, suggested the molecular marker prediction of selectivity and specificity in drug treatment." (PMID 31164891, 2019). "Evaluation of tumor-infiltrating lymphocyte cells in a melanoma microenvironment showed an enrichment of CD8+ T cells, activated CD4 memory T cells, activated NK cells in the LRP1B mutant type group, while neutrophils were enriched in the wild-type group." (PMID 34577535, 2021). "The correlation of LRP1B with TMB and immunotherapy efficacy has been confirmed in multiple cancers, including lung cancer, melanoma and other solid tumors." (PMID 35069585, 2021). "Besides, a decreased predicated binding affinity (IC50) were also detected in LRP1B mutant samples, although these difference was not statistically significant (median binding affinity, melanoma: 166 vs. 170, p = 0.168; NSCLC: 164 vs. 167, p = 0.392)." (PMID 31164891, 2019).
lung cancer (35 papers, 2010 to 2025). A malignant neoplasm involving the lung. "LRP1B acts as a tumor suppressor gene encoding low‐density lipoprotein receptor and is frequently altered in many types of cancer, including non‐small cell lung cancer, esophageal cancer, uterine cancer, and bladder cancer." (PMID 37727135, 2024). "LRP1B has been reported to be frequently mutated in numerous types of cancers, including lung cancer." (PMID 36874015, 2023). "LRP1B mutations are significantly associated with prognosis and with a higher tumor mutation burden in non‐small cell lung cancer (NSCLC)." (PMID 36282125, 2023). "In the training set, RNF213, KMT2D, CSMD3 and LRP1B were mutated more frequently in early‐stage lung cancer than in benign disease." (PMID 33200540, 2021). "KMT2D, CSMD3 and LRP1B were mutated in 15%, 10% and 10% of lung cancer patients, but KMT2D and CSMD3 were mutated in 25% and 12.5% of benign diseases." (PMID 33200540, 2021). "In the training set, the RNF213, KMT2D, CSMD3 and LRP1B genes were mutated more frequently in early‐stage lung cancer (27 cases) than in benign nodules (15 cases) (P < 0.05)." (PMID 33200540, 2021). "As LRP1B mutation was common in lung cancer, we aggregated whole exome sequencing data from three studies of NSCLC immunotherapy to corroborate the results." (PMID 31164891, 2019). "This implies that identifying LRP1B mutation may play a critical part in the pathogenesis of lung cancer and immune response." (PMID 38370388, 2024). "Single gene mutations in LRP1B were found to be associated with high TMB in lung cancer, which may be associated with favorable outcomes with immune checkpoint inhibitors." (PMID 36685819, 2022). "LRP1B was one of the frequently mutated genes in multiple cancer types, such as gastric, liver, breast, and pancreatic cancer, and also lung cancer." (PMID 35884443, 2022). "Together, these findings suggest that Lrp1b and/or Fgfr2 may be linked to the propensity of tumor formation in the A/J mouse model of lung cancer." (PMID 35295134, 2021). "Also in other tumor entities like thyroid cancer, gastric cancer, lung cancer and oral cancers silencing or loss of LRP1B was observed." (PMID 22761851, 2012). "Furthermore, LRP1B is not only a frequently deleted gene in tumors but it is also frequently point mutated in lung cancer, and its promoter is frequently methylated in several cancer types." (PMID 20942901, 2010). "Low-density lipoprotein (LDL) receptor-associated protein 1B (LRP1B), a member of the LDL receptor family, is often inactivated in lung cancer." (PMID 36685819, 2022). "A recent study showed that the lung cancer patients with co-mutation of FAT3 and LRP1B had significantly prolonged immunotherapy PFS, which indicated that co-mutation of FAT3 and LRP1B is a promising biomarker to predict the efficacy of immunotherapy." (PMID 35372348, 2022). "The number of the test genes RNF213, KMT2D, CSMD3 and LRP1B detected in lung cancer samples was five, five, three and two, respectively." (PMID 33200540, 2021). "LRP1B, KMT2D, RNF213 and CSMD3 gene mutations were significantly more common in lung cancer than in benign disease (P < 0.05)." (PMID 33200540, 2021). "LRP1B gene encodes for an LDL receptor and acts as a putative tumor suppressor in lung cancer whose function is only partially defined." (PMID 34071259, 2021). "Of note, a novel low density-lipoprotein receptor-related protein 1B (LRP1B) mutation was identified and significantly increased prevalence in lung cancer with COPD." (PMID 31336878, 2019). "Lung cancer was the next most affected, but curiously had a different spectrum of frequencies, with LRP1B being the most frequently deleted CFS-like gene at 4%." (PMID 23805207, 2013).